GLP1R (glucagon like peptide 1 receptor)
Diseases named in the same sentence as GLP1R in open-access papers (continued):
Sharing a sentence is not in itself a finding about the gene and the disease.
diabetes (continued). "In addition, chronic administration of GLP1R agonists can alleviate the development of adverse cardiac remodeling in myocardial infarction, hypertension, and diabetes mellitus." (PMID 38732142, 2024). "This significant interaction between EGF and GLP-1R could potentially be leveraged for enhancing β-cell proliferation and function, offering promising insights for diabetes treatment strategies." (PMID 39610526, 2024). "A class of diabetes treatment medications called glucagon-like peptide-1 receptor agonists (GLP-1RA) has seen recent widespread use for people with diabetes or obesity, with efficacy for improved glycemic control, weight loss, and reduced risk of cardiovascular events." (PMID 39492845, 2024). "In this genetic association study of 353 153 adults, higher genetic GLP1R gene expression as a proxy for GLP-1RAs was associated with a small reduction in the risk of kidney disease progression, even after adjusting for obesity and diabetes." (PMID 39453656, 2024). "Our present study identifies an important role for GLP-1R in diabetes treatment, highlights the potential of natural plant-derived substances in the treatment of diabetic cognitive impairment, and provides new ideas for the future development of drugs to treat diabetic cognitive dysfunction." (PMID 39257395, 2024). "Entry into the brain and subsequent activation of GLP1-R was more rapid when the agonist was given IP compared with subcutaneously (SC), the usual route of administration for patients with diabetes, at 30 mins (****p < 0.0001 IP vs SC) and 2 h (**p = 0.0024 IP vs SC)." (PMID 38783166, 2024). "Alternatively, could ACH have been elicited by the use of incretin-based anti-diabetes medications, namely glucagon-like peptide-1 receptor agonists (GLP-1Ra), subsequently contributing to the development of glucagon-producing NET?" (PMID 39309109, 2024). "Although GLP-1R agonists exhibit protective and regulatory effects on blood glucose levels, they have been positively correlated with tumor progression in patients with diabetes." (PMID 38801466, 2024). "Chronic stimulation of the GLP1R can alleviate diabetes-induced adverse remodeling of the heart." (PMID 38732142, 2024). "The sodium/glucose cotransporter 2 (SGLT2) inhibitor empagliflozin and glucagon-like peptide-1 receptor (GLP1R) agonist semaglutide, medications originally developed to treat diabetes and/or obesity, have demonstrated clinically significant cardiovascular benefits." (PMID 39081779, 2024). "The guidelines of the American Diabetes Association (ADA) and European Association for the Study of Diabetes (EASD) suggest that patients with obesity, T2D, and CKD need either glucagon-like peptide 1 receptor analogues (GLP1RA) or sodium-glucose cotransporter-2 inhibitors (SGLT2i)." (PMID 38365744, 2024). "The management of diabetes and renal failure is changing thanks to the appearance of new drugs such as glucagon-like peptide 1 receptor agonists (GLP1-RA) and sodium-glucose cotransporter type 2 inhibitors (SGLT2i) that have benefits in terms of survival and cardiorenal protection." (PMID 37374048, 2023). "Several classes of drugs, including hypoglycemic, agents renin-angiotensin system (RAS) blockers, sodium-glucose cotransport protein-2 inhibitors (SGLT2i), and glucagon-like peptide-1 receptor (GLP-1R) agonists, have been shown to effectively manage diabetes and DN." (PMID 37143722, 2023). "For diabetes treatment, nine (6%) patients were prescribed diet and exercise only, 95 (62%) were taking oral hypoglycemic agents alone, 35 (23%) were taking insulin, and 22 (15%) were taking glucagon-like peptide-1 receptor agonists." (PMID 37993771, 2023). "Of the diabetes medications studied and implemented in clinical settings, glucagon-like peptide-1 receptor agonist (GLP1-RA) drugs have been shown to not only help control HbA1c in diabetes but have also demonstrated numerous cardiovascular, hepatic, and renal benefits." (PMID 37090383, 2023).
diabetes (continued). "Agonists of the glucagon-like peptide-1 receptor are used to treat diabetes and obesity." (PMID 37813859, 2023). "The development of new techniques for retinal imaging and functional assessment will help us to detect early changes and further to clarify whether therapies based on GLP-1R activation are good or bad for the human diabetic retina." (PMID 37680468, 2023). "There are currently seven GLP-1R agonists (GL1-RAs) approved for the treatment of diabetes." (PMID 37239313, 2023). "Data from the 2003–2019 Medical Expenditure Panel Survey (MEPS) showed that NH Black adults consistently had the lowest utilization of medications used in the management of diabetes and obesity, such as glucagon-like peptide-1 receptor agonists (GLP-1 RA), among all racial groups." (PMID 37998831, 2023). "Further studies of agonists that selectively modify these distinct signalling pathways could improve GLP-1R targeting therapies for diabetes and obesity." (PMID 36943057, 2023). "GLP-1R positive cell ratio in islets is crucial for the blood glucose level of diabetes." (PMID 37520251, 2023). "Considering the physiological importance of GLP-1 in controlling islet cell function, appetite, inflammation and cardiovascular pathophysiology, the development of GLP-1 receptor (GLP-1R) agonists was a crucial step in obesity and diabetes treatment strategies." (PMID 35328759, 2022). "Fortunately, pharmacological interventions such as glucagon-like peptide-1 receptor agonists (GLP-1RA) that treat the obesity-diabetes-OSA triad can make substantial inroads in reversing the trends in morbidity and cost associated with obesity-related illnesses." (PMID 36013401, 2022). "Therefore, we evaluated the therapeutic efficacy of a new recently licensed GLP-1R agonist diabetes drug in a mouse model of INAD." (PMID 35970890, 2022). "GLP-1R agonists may improve the neurological function of patients, especially those with diabetes, by regulating the polarization of microglia." (PMID 35280691, 2022). "All these results indicate that GLP-1 participates in the regulation of vascular aging-related diseases and GLP-1R agonists could be recommended for people with diabetes and high cardiovascular risks." (PMID 36225176, 2022). "GLP-1R, therefore, plays a critical role in diabetes and cardiovascular disease." (PMID 35154099, 2022). "Patients with asthma prescribed GLP1 R agonists for diabetes had fewer asthma exacerbations." (PMID 36457601, 2022). "Furthermore, the GLP-1R agonists were already proven safe in clinical treatment for diabetes and obesity, it is worthwhile to develop antagonists of GLP-1R for PNETs treatment." (PMID 35954231, 2022). "It suggested that microglial GLP-1R signaling-mediated neuroinflammation may be closely related to the development of diabetes with depression." (PMID 36615696, 2022). "Studies have suggested that in addition to diabetes, GLP-1R agonists may also have a beneficial effect on many other diseases such as cardiovascular disease, central nervous disorder, and tumors." (PMID 36569936, 2022). "Glucagon-like peptide-1 receptor agonist (GLP-1RA) is a new type of drug for treating diabetes." (PMID 35434139, 2022). "Thus, GLP-1R agonists prevent or delay the development of diabetes in both db/db mice and Goto-Kakizaki rats, and diminish the severity of diabetes in rats after partial pancreatectomy or neonatal administration of streptozotocin." (PMID 35055431, 2022). "The occurrence of GI symptoms in patients with diabetes may represent an adverse effect of glucose-lowering medications, such as metformin, acarbose and glucagon-like peptide-1 receptor agonists." (PMID 36079764, 2022). "In addition, immunohistological staining of GLP-1R also presented higher GLP-1R expression in the protein level in combination therapy in an early phase of diabetes and its protein expression levels were quite similar to mRNA expression levels in all groups." (PMID 34373487, 2021).
diabetes (continued). "Liraglutide did not cause symptomatic hypoglycaemia (in a predominantly non-diabetes trial cohort) and significantly reduced weight and stimulated net improvements in lipid profile, in line with the known effects of injectable GLP-1R agonists." (PMID 33579317, 2021). "Brunton reported an RCT testing the effectiveness of GLP-1R agonists in diabetes." (PMID 33919067, 2021). "Therefore, we suggest that the changes in the effects of GCGR and GLP-1R induced by metabolic stress should also be considered when designing GCGR- and GLP-1R-combined agonists for the treatment of diabetes." (PMID 34572144, 2021). "Glucagon-like peptide 1 receptor (GLP-1R) agonists may have a similar anti-inflammatory effect in patients with diabetes and COVID-19, as they are known to reduce the levels of several anti-inflammatory markers." (PMID 35002970, 2021). "According to findings from a limited number of preclinical and clinical studies, glucagon-like peptide-1 receptor agonists (GLP-1RAs) could be a promising strategy in reducing the incidence of CRC in patients with diabetes." (PMID 34830295, 2021). "We hypothesized that combination of a TZD insulin sensitizer and the glucagon-like peptide-1 receptor agonist liraglutide would more significantly improve mouse models of diabetes and nonalcoholic steatohepatitis (NASH)." (PMID 34022222, 2021). "ACEIs, ARBs, and GLP-1R agonists may lead to many beneficial effects in patients with hypertension, diabetes, and obesity during COVID-19 by ACE2 upregulation and NHE inhibition." (PMID 34285709, 2021). "Glucagon-like peptide-1 receptor agonists (GLP1Ras) are a class of antihyperglycemic drugs that have shown benefits for heart function and reduction of the incidence of major adverse cardiac events (MACEs) in patients with diabetes." (PMID 34445425, 2021). "For instance, GLP-1 receptor (GLP-1R) agonists are usually administered to patients with diabetes." (PMID 34094645, 2021). "In addition to significantly reducing blood glucose, GLP‐1R agonists can also reduce weight, blood pressure, improving the function of β cell, which showed the potential to delay the progress of diabetes and reduce cardiovascular complications." (PMID 33300675, 2021). "SGLT2i and GLP1R agonists open new avenues to the successful treatment of patients with diabetes, focusing not only on glycemic targets, but also cardiovascular, cerebrovascular and renal outcomes (which will translate into improved survival and preserved quality of life)." (PMID 34639160, 2021). "Therefore, GLP-1R agonists are expected to improve endothelial function through reducing glucose fluctuations in patients with diabetes mellitus." (PMID 34439553, 2021). "Also, glucagon-like peptide-1 receptor agonists have been shown to reduce the risk for CVD and CKD outcomes in patients with high CVD risk and diabetes." (PMID 33648518, 2021). "Treatment with liraglutide, metformin, or their combination significantly decreased GLP-1R protein expression when compared to the untreated T1DM group, suggesting that AMPK could be a potential regulator of GLP-1R in diabetes." (PMID 34680477, 2021). "Indeed, GLP-1R agonists have been shown to augment endothelial function in patients with diabetes mellitus." (PMID 34439553, 2021). "The findings of such a study could provide evidence as to whether existing GLP-1R agonists affect glaucoma incidence or progression among patients with diabetes." (PMID 33147455, 2020). "It is still unknown how stress influences central GLP-1R signaling in metabolic pathologies, such as obesity or diabetes." (PMID 33126672, 2020). "GLP-1R agonists have been applied widely in the clinical treatment of diabetes nowadays." (PMID 32903510, 2020). "Critically, this translated into significant reductions in exendin-4-induced insulin secretion, indicating that GLP-1R palmitoylation may play an important role in glucose homeostasis or responses to pharmacological GLP-1R agonists in diabetes." (PMID 31430273, 2019).
diabetes (continued). "In diabetes patients with established CVD or at high cardiovascular risk, GLP1R agonists could be a preferred anti-hyperglycemic agent after considering drug-specific and patient factors." (PMID 30223891, 2018). "Overall, these results demonstrate that GLP-1R may be a novel target for the treatment of OA, particularly in patients with diabetes mellitus." (PMID 29434185, 2018). "One investigation has shown that the incretin-based therapeutic agents with blood-glucose-lowering effects such as agonists of glucagon-like peptide 1 receptor improve pancreatic islet function, exhibit renoprotection in diabetes and also inhibit onset of the morphological abnormalities of DR." (PMID 29987200, 2018). "For patients with T2D uncontrolled on oral antidiabetic drugs (OADs) or glucagon-like peptide 1 receptor agonists (GLP-1RAs), the American Diabetes Association (ADA) and the European Association for the Study of Diabetes (EASD) guidelines recommend the use of basal insulin as an alternative option." (PMID 29408938, 2018). "Extended logically from these findings, we speculated that the potent anti-inflammatory and proangiogenic effects mediated by Glp-1R analogues might potentiate the healing of gastric ulcer in rats with experimental diabetes." (PMID 29095895, 2017). "The phenomenon could be readily explained by the expression of GLP-1R in islets of patients at different stages of their diabetes." (PMID 28801559, 2017). "As an agonist of GLP-1R, exendin-4 ameliorates diabetes in db/db mice through GLP-1R." (PMID 28122026, 2017). "GLP-1R agonist exendin-4 is in clinical use for the treatment of diabetes and several studies indicated that it may be useful in the treatment of stroke." (PMID 26863436, 2016). "It will be interesting to understand the functional consequences of these changes, which are relevant for possible application in the development of GLP-1R agonists for medical application in diabetes treatment and for better understanding of the function of these changes in monotreme GLP-1." (PMID 27898108, 2016). "Furthermore, we showed for the first time that patients with long standing T2DM demonstrated decreased expression of their gastric glands GLP-1R indicating that T2DM diabetes affects the expression of extrapancreatic GLP-1R." (PMID 25893200, 2015). "However, nutrient and chemical induced diabetes resulted in opposite alterations of glandular GLP-1R expression." (PMID 25893200, 2015). "Moreover, the GLP-1R agonist, liraglutide, has been shown to suppress oxidative stress in rats with streptozotocin-induced diabetes." (PMID 25976560, 2015). "Taken together, our data may suggest that combined early STZ and late hyperglycemic mediated cytotoxicity reduce the expression of GLP-1R in gastric glands of rats with STZ-induced diabetes." (PMID 25893200, 2015). "Thus, HE diet- and STZ-induced diabetes result in distinct and opposite alterations of GLP-1R expression in the principal gastric glands." (PMID 25893200, 2015). "Glucagon-like peptide-1 receptor agonists (GLP1-RA) have been shown to be associated with improved cardiovascular outcomes, weight loss, and reduced inflammation and may be considered as first-line therapy in patients with PsA and diabetes or obesity." (PMID 40137170, 2025). "The same drugs can be employed for managing obesity, both in patients with diabetes and without it, because various studies have revealed that, also in patients without diabetic disease, GLP1-R agonists are effective in promoting weight loss in relation to a placebo." (PMID 41516231, 2025). "Molecular docking prediction studied results showed that all 27 active compound molecules from mango leaves could bind to the key interacting residues of 3 diabetes-causing enzymes, including GSK3β, DPP-4, and GLP-1R with the promising binding affinities (Table A1)." (PMID 41465578, 2025).
diabetes (continued). "In addition, the activation of GLP-1R is to be explored in other diseases such as Alzheimer’s disease, Parkinson’s disease, non-alcoholic fatty liver disease and non-alcoholic steatohepatitis in addition to traditional diabetes treatment." (PMID 40520185, 2025). "Likewise, the oligomerization of the glucagon-like peptide-1 receptor (GLP-1R) with the glucose-dependent insulinotropic polypeptide receptor (GIPR) in regulating post-endocytic insulin secretion offers a promising new approach for diabetes treatment." (PMID 40362321, 2025). "Glucagon-like peptide-1 receptor agonists, a type of diabetes medication, could potentially aid in preserving fertility for obese patients with endometrial cancer by lowering body mass index, inflammation, and insulin resistance, hence increasing likelihood of future pregnancy." (PMID 39429275, 2024). "Of interest, glucagon-like peptide-1 receptor agonists—known for beneficial effects on metabolism and weight control—may also improve depressive symptoms in individuals with diabetes or obesity, and glucagon-like peptide-1 receptors are stimulated by glutamine." (PMID 39199532, 2024). "Glucagon-like peptide-1 receptor agonists (GLP-1 RAs), especially semaglutide (famously known as Ozempic® or Wegovy®), have become very popular in recent years for weight loss, even though their initial indication is for the management of the patient with diabetes mellitus." (PMID 39872560, 2024). "Various dual/triple agonists for glucagon-like peptide-1 receptor (GLP-1R), which also target the gastric inhibitory peptide receptor and glucagon receptor, have recently been explored to increase treatment efficacy for both diabetes and obesity in the clinical setting." (PMID 37660070, 2023). "Probably, GLP-1R agonism could be a competent therapeutic strategy to combat obesity-related diabetes with minimal side effects (such as nausea and vomiting), also because of its beneficial effects on the nervous and cardiovascular systems and metabolic equilibrium." (PMID 37435495, 2023). "Amongst patients with diabetes, the most common diabetes medications were insulin and insulin analogs (53.7%), biguanides (40.8%), and sulfonylureas (22.3%); use of sodium–glucose co-transporter inhibitors (3.2%) and glucagon-like peptide-1 receptor agonists (1.1%) was less common." (PMID 37592272, 2023). "Since the GCGR agonists have emerged as potential therapeutic options for managing obesity, diabetes and other metabolic disorders, one intriguing development in this field is the discovery of unimolecular dual agonists that simultaneously activate both the GLP1R and the GCGR." (PMID 38093651, 2023). "Hence, bioactive peptidescotargeting GCGR and GLP-1R may remediate the blood glucose and fattyacid metabolism imbalance, tackling both diabetes and obesity to supersedecurrent monoagonist therapy." (PMID 37523325, 2023). "Thus, we determined that microglial pyroptosis-related neuroinflammation may be the therapeutic target for the effect of GLP-1R on diabetes with depression." (PMID 36615696, 2022). "From two of our previous studies, we also reported that using the glucagon-like peptide-1 receptor (GLP-1R) agonist, liraglutide, which is widely applied in diabetes therapeutics, could prevent and reverse monocrotaline (MCT)-induced PAH by suppressing ET-1 and enhancing the eNOS/sGC/PKG pathways." (PMID 35740436, 2022). "Furthermore, in addition to the pancreas, GLP-1R is expressed in the other organs, and GLP-1R is expected to exert pleiotropic effects for organ protections from injury due to diabetes via improvement of various metabolic disorders or activation of another molecular pathways." (PMID 35524186, 2022). "Additionally, we will investigate how failure of the interplay between alpha- and beta-cell function contributes to the pathophysiology of diabetes, and furthermore, we will highlight how intra-islet paracrine signaling contributes to the effects of pharmaceutical targeting of the GLP-1R." (PMID 35957816, 2022).